PIERCE2 (piercer of microtubule wall 2)
Description:
Microtubule inner protein involved in the attachment of outer dynein arms (ODAs) to dynein-decorated doublet microtubules (DMTs) in cilia axoneme, which is required for motile cilia beating.
Synonyms: C15orf65; FLJ27352; C14orf65
Tractability: Small molecule: a structure with a bound ligand is known.
Gene: Protein-coding gene on chromosome 15 (55,408,495 to 55,418,798, forward strand). Ensembl gene ENSG00000261652.
Subcellular location: Cytoplasm, cytoskeleton, cilium axoneme; Cytoplasm, cytoskeleton, flagellum axoneme
Gene Ontology:
Molecular function: protein binding
Biological process: axoneme assembly; cilium movement; determination of left/right symmetry; flagellated sperm motility
Cellular component: axonemal microtubule; axonemal A tubule inner sheath; sperm flagellum; axoneme
Genetic constraint (gnomAD): Loss-of-function variants: 5 observed, 3.73 expected, observed/expected ratio (o/e) 1.34, 90% interval 0.65 to 1.91. That is too few expected variants to judge how well the gene tolerates losing a copy. Missense variants: 125 observed, 127.71 expected, observed/expected ratio (o/e) 0.98, 90% interval 0.85 to 1.13. Synonymous variants: 42 observed, 43.61 expected, observed/expected ratio (o/e) 0.96, 90% interval 0.75 to 1.25.
Homologues: Orthologues: chimpanzee PIERCE2 (99% identical), macaque PIERCE2 (96% identical), rabbit PIERCE2 (87% identical), dog PIERCE2 (85% identical), pig PIERCE2 (85% identical), guinea pig PIERCE2 (69% identical), rat Pierce2 (66% identical), mouse Pierce2 (65% identical), tropical clawed frog pierce2 (41% identical), Drosophila melanogaster CG34107 (22% identical). Paralogues in human: PIERCE1 (26% identical).
Diseases named in the same sentence as PIERCE2 in open-access papers:
PIERCE2 is named in the same sentence as 2 diseases in open-access papers, as found by Europe PMC text mining. Sharing a sentence is not in itself a finding about the gene and the disease. The quoted sentences say what the papers report.
ciliopathies (1 paper, 2021). "Our functional characterization demonstrates that the Pierce1 and Pierce2 genes are important for ciliary motility and that their genetic loss causes ciliopathy-like phenotypes." (PMID 34715025, 2021). "The structural information also provides a framework to interrogate the roles of individual axonemal proteins and their contribution to ciliary motility and ciliopathies, as we demonstrate for Pierce1 and Pierce2." (PMID 34715025, 2021).
PIERCE2 also shares sentences with these, for which no sentence is quoted: cancer (1 paper).